SOCS3 (suppressor of cytokine signaling 3)
Diseases named in the same sentence as SOCS3 in open-access papers (continued):
Sharing a sentence is not in itself a finding about the gene and the disease.
Spondyloarthritis (2 papers, 2018 to 2021). "Further investigations are needed to explore the precise mechanisms underlying functional involvement of SOCS3 in spondyloarthritis, determine its diagnostic value in spondyloarthritis, and pave the way for effective treatment of this kind of diseases." (PMID 30487798, 2018). "Our results suggest that SOCS3 is involved in development of spondyloarthritis through regulating osteoblast differentiation." (PMID 30487798, 2018). "This study aimed to develop an ideal animal model for an insight into mechanism of spondyloarthritis and functional relevance of SOCS3 in spondyloarthritis." (PMID 30487798, 2018). "Using this mouse model, we found that targeted disruption of SOCS3 expression resulted in severe spondyloarthritis in mice induced by minicircle DNA expressing IL23." (PMID 30487798, 2018). "As a consequence, much severer spondyloarthritis was induced by injected minicircle DNA expressing IL23 in SOCS3 knockdown transgenic mice as compared with wild type control." (PMID 30487798, 2018). "Together with previous studies, the data also presented clues that the upregulated SOCS3 in patients may be the results of the battle between normal and abnormal cells during the course of spondyloarthritis." (PMID 30487798, 2018). "Therefore, SOCS3 is a crucial regulator of osteoblast differentiation in spondyloarthritis." (PMID 34746233, 2021).
subarachnoid hemorrhage (2 papers, 2014 to 2023). A serious neurological disorder characterized by intracranial hemorrhage into the subarachnoid space. "A previous study has found that increased expression of MFG-E8 can downregulate the phosphorylation of STAT3 and upregulate the expression of SOCS3, then promote M2 polarization and exert an anti-inflammatory effect after subarachnoid hemorrhage." (PMID 36717543, 2023).
uveal melanoma (2 papers, 2023). A melanoma derived from melanocytes of the uveal tract. "A very recent study on uveal melanoma cells demonstrates that overexpression of SOCS3 can partially inhibit the PTK6-driven uveal melanoma cell proliferation." (PMID 37509364, 2023). "This indicated that SOCS3 was involved in the autophagy of PTK6 in uveal melanoma." (PMID 36690663, 2023).
viral hepatitis (2 papers, 2022 to 2025). An acute or chronic inflammation of the liver parenchyma caused by viruses. "The SOCS1 and SOCS3 proteins are involved in immune response and inhibit protective interferon signaling in viral hepatitis." (PMID 35626153, 2022).
viral myocarditis (2 papers, 2019 to 2021). Myocarditis that is caused by an infection with a viral agent. "We have also demonstrated that SOCS3 is rapidly induced during pressure overload, viral myocarditis, post-MI ventricular remodeling, and I/R injury in mice." (PMID 34292971, 2021). "In contrast, miR-30a and miR-181d were found to promote myocardial inflammation by targeting suppressor of cytokine signaling 3 (SOCS3), and an inhibition of these miRNAs significantly decreases mortality in a murine model of CVB3-induced viral myocarditis." (PMID 31671621, 2019).
abdominal aortic aneurysm (1 paper, 2024). Enlargement and ballooning of the vessel that supplies arterial blood to the abdomen, pelvis and legs. "We obtained six macrophage hub genes (IL-1B, CXCL1, SOCS3, SLC2A3, G0S2, and CCL3) that can effectively diagnose abdominal aortic aneurysm." (PMID 38867262, 2024).
acute leukemia (1 paper, 2016). A clonal (malignant) hematopoietic disorder with an acute onset, affecting the bone marrow and the peripheral blood. "Due to the documented role of SOCS3 silencing in other types of cancer, this type of therapeutic intervention could be applicable to the treatment of acute leukemia and solid tumors as well." (PMID 27107422, 2016).
adenovirus infection (1 paper, 2023). "For example, influenza A virus, HSV, and RSV can suppresses IFN-I production and response by stimulating SOCS3 expression, consistent with our data showing that SOCS3 was upregulated after adenovirus infection." (PMID 37017816, 2023). "Transcriptome sequencing showed that the expression levels of SOCS3, OASL, ISG15, and IFIT1 increased significantly over time, especially at 48 hpi (except SOCS3) and 72 hpi, suggesting that these genes might play an important role in adenovirus infection." (PMID 37017816, 2023). "Of these, SOCS3, OASL, ISG15, and IFIT1 were found to be involved in the process of adenovirus infection and were thus regarded as candidate genes." (PMID 37017816, 2023).
adrenocortical carcinomas (1 paper, 2023). "The upregulation of miR-483-5p was also associated with poorer disease-specific survival in patients with adrenocortical carcinomas, and the expression of miR-483-5p promotes HCC cell proliferation by targeting the suppressor of cytokine signaling 3 (Socs3)." (PMID 36980601, 2023).
Adult onset (1 paper, 2016). Onset of disease manifestations in adulthood, defined here as at the age of 16 years or later. "Therefore, to explore the combined loss of SOCS1 and SOCS3 in inflammation, we determined the effects of post-natal inactivation of SOCS3 on disease development and severity in the Ifng-/-;Socs1-/- model of adult-onset inflammatory disease." (PMID 27583437, 2016).
alopecia areata (1 paper, 2017). Loss of scalp and body hair involving microscopically inflammatory patchy areas. "SOCS3 is downregulated in the skin of alopecia areata patients and murine autoimmune alopecia model." (PMID 28418931, 2017). "Furthermore, SOCS3 treatment prevents the development of alopecia areata in the graft model." (PMID 28418931, 2017). "In the present study, we identified that suppressor of cytokine signaling-3 (SOCS3), a classical inhibitor of cytokine signaling, significantly inhibits CD8+T cell maturation, interferon-γ (IFN-γ) production and alopecia areata." (PMID 28418931, 2017). "The SOCS3 level is negative correlation with the Fas and MHC I level in patients with alopecia areata." (PMID 28418931, 2017).
alveolitis (1 paper, 2020). "Compared with the BLM group, the degree of alveolitis and fibrosis improved significantly, and the expression of p-JAK1 and p-STAT1 decreased; conversely, the expression of SOCS3 increased in the treatment group." (PMID 32908556, 2020).
amyloid (1 paper, 2018). "3xTg mice were injected at 3–4 months with AAV-GFP or AAV-SOCS3 + AAV-GFP (3xTg-GFP and 3xTg-SOCS3 mice respectively) and studied 5 months later, when they display synaptic deficits and higher GFAP levels but before amyloid plaque and Tau deposition." (PMID 30322407, 2018). "SOCS3 reduces GFAP and STAT3 expression in APP mice, even around amyloid plaques (star)." (PMID 30322407, 2018).
anaphylaxis (1 paper, 2025). An acute hypersensitivity reaction that occurs from exposure to an allergen. "Thus, it is necessary to examine the role of SOCS3 in anaphylaxis in the future." (PMID 40005151, 2025).
anaplastic thyroid cancer (1 paper, 2015). "Therefore it is reasonable to suggest that SOCS3 generally acts as a cell survival factor, except in anaplastic thyroid cancer." (PMID 25849377, 2015).
arteriosclerotic vascular disease (1 paper, 2015). "SOCS3-related miRNAs (miR-30a, miR-30e and miR-19b) are upregulated in atherosclerotic tissues in the mouse arteriosclerotic vascular disease (ASVD) model." (PMID 25997679, 2015).
autoimmune encephalitis (1 paper, 2022). Inflammation of the brain secondary to an immune response triggered by the body itself. "Overexpression is shown to downregulate inflammatory cytokine production by astrocytes in the autoimmune encephalitis mouse model by reducing SOCS3 expression, a protein also found elevated in AMN patient PBMCs." (PMID 36341174, 2022).
avian influenza (1 paper, 2014). Infection of domestic and wild fowl and other birds with influenza A virus. "The authors showed that the lower susceptibility of pigs to contemporary Eurasian highly pathogenic avian influenza (HPAI) H5N1 virus infection is linked to SOCS3 induction." (PMID 24712747, 2014).
babesiosis (1 paper, 2023). Babesiosis refers to a condition caused by microscopic parasites that infect the red blood cells. "The highest level of SOCS3 expression was detected in dogs with severe babesiosis (Babesia 2), and was relatively high also in dogs with mild/moderate babesiosis and dogs infected only with D. repens." (PMID 36739305, 2023). "In dogs with mild/moderate babesiosis the expression of GATA3 was highest, while in dogs with advanced babesiosis the highest expression of INF-γ and SOCS3 was recorded." (PMID 36739305, 2023).
bladder tumors (1 paper, 2017). "Downstream IL-6 signaling JAK1, STAT3, and SOCS3 were consistently upregulated in the same bladder tumors with low IL-6 levels suggesting IL-6 independent activation of the JAK1/STAT3 pathway." (PMID 29242529, 2017).
brain injuries (1 paper, 2022). "Turovsky and co-workers reported that selenium nanoparticles are able to protect cortical astrocytes and neurons against ischemic brain injuries inhibiting apoptosis inactivating caspase 3 and recruiting nuclear factors Nrf2 and SOCS3/STAT3." (PMID 35216387, 2022).
breast invasive carcinoma (1 paper, 2022). "SOCS3 amplification occurred in several cancers, among which the most common type of cancers was breast invasive carcinoma, followed by ovarian serous cystadenocarcinoma, liver hepatocellular carcinoma, lung squamous cell carcinoma, and LGG." (PMID 35600392, 2022).
cardiogenic shock (1 paper, 2025). "Changes in SOCS3 expression were determined in patients with septic shock (SS) and cardiogenic shock (CS) at the following three time points: within 16 h of ICU admission (T1), 48 h after study enrollment (T2), and on day 7 after ICU admission or before discharge from the ICU (T3)." (PMID 40808951, 2025).
Cerebral ischemia (1 paper, 2023). Restriction of arterial blood supply to the brain associated with insufficient oxygenation to support the metabolic requirements of the tissue. "CSN3 was found to reduce neuroinflammation during cerebral ischemia/reperfusion injury through stabilizing suppressor of cytokine signaling 3 SOCS3." (PMID 37597109, 2023).
Chagas disease (1 paper, 2013). A parasitic infection caused by Trypanosoma cruzi. "Our study reports the first evidence that T. cruzi up- regulates SOCS-3 expression and highlights the relevance of IL-10 in the modulation of pro-inflammatory response of cardiomyocytes in Chagas’ disease." (PMID 24260222, 2013).
chondrosarcoma (1 paper, 2022). A malignant cartilaginous matrix-producing mesenchymal neoplasm arising from the bone and soft tissue. "After treatment with shikonin, both chondrosarcoma cell lines revealed a significant reduction in SOCS3 expression." (PMID 35820864, 2022).
choriocarcinoma (1 paper, 2017). An aggressive malignant tumor arising from trophoblastic cells. "SOCS-3 have been identified as important regulators of ERK/MAPK pathway and STAT3 signaling in undifferentiated Rcho-1 cells, which were derived from rat choriocarcinoma." (PMID 29234375, 2017).
chronic eosinophilic leukemia (1 paper, 2013). "SOCS3, but not SOCS2, was also upregulated in a chronic eosinophilic leukemia bearing PCM1-JAK2, highlighting its role as a central signalling target of JAK2 translocation neoplasia." (PMID 23372669, 2013).
dysplasia (1 paper, 2023). A usually neoplastic transformation of the cell, associated with altered architectural tissue patterns. "Conversely, other groups found lower Socs3 expression to be associated with IBD-associated dysplasia as well as an increased susceptibility to IBD." (PMID 37283760, 2023).
E. coli infection (1 paper, 2019). "As for the eight common genes screened out in all four datasets, CEACAM1, GK, PFKFB3, and TNFAIP6 emerged repeatedly in the S. aureus group, but CEACAM1, IL18RAP, LILRA5, PFKFB3, PSTPIP2, and SOCS3 emerged in the E. coli infection." (PMID 31093495, 2019).
encephalitis (1 paper, 2014). An acute inflammatory process affecting the brain parenchyma. "It was further confirmed that SOCS3 proteins were induced in mice brain by JEV and are in accordance with the expression of SOCS3 and encephalitis in vivo." (PMID 25390684, 2014).
eosinophilic esophagitis (1 paper, 2020). Eosinophilic esophagitis (EoE) is a chronic, allergic disease of the esophagus characterized clinically by symptoms of esophageal dysfunction (including vomiting, dysphagia, feeding disorders, food impaction and abdominal pain) which persist after treatment with proton pump inhibitors (PPIs). "In their studies, SOCS1 and SOCS3 mRNA levels were significantly increased in esophageal biopsies collected from eosinophilic esophagitis patients." (PMID 32408627, 2020).
Erythema (1 paper, 2023). Redness of the skin, caused by hyperemia of the capillaries in the lower layers of the skin. "There was no statistical correlation between SOCS-3, demographic and clinical data of the patients regarding their age, sex, duration, BSA, erythema, scaling in lesional and perilesional skin." (PMID 35226171, 2023).
Erythrocytosis (1 paper, 2013). "JAK2 V617F mutation and methylation analysis of SOCS1/SOCS3 CpG islands were performed in 45 cases of MPNs, 42 cases of secondary erythrocytosis/thrombocythemia, and for 29 control individuals." (PMID 24385747, 2013). "Hypermethylation of the SOCS3 promoter was identified in 5 out of 19 (26.3%) PV cases, 2 out of 21 (9.5%) ET cases, 1 out of 5 (20%) PMF cases, and 9 out of 42 (21.4%) cases of secondary erythrocytosis/thrombocythemia." (PMID 24385747, 2013).
gallbladder carcinoma (1 paper, 2021). "Leptin and its receptor LEPR promote the proliferation and metastasis of gallbladder carcinoma, which may participate in the regulation of MMPs and the VEGF family through the SOCS3/JAK2/STAT3 pathways." (PMID 33397392, 2021).
gastric adenoma (1 paper, 2022). A neoplastic polyp that arises from the stomach. "In Gp130F/F mice, a disruption of the Socs3-dependent negative feedback loop on the shared IL-6 cytokine family gp130 receptor subunit results in excessive STAT3 signaling that promotes the spontaneous development of gastric adenomas from 6 weeks of age." (PMID 36552868, 2022).
hepatitis B (1 paper, 2011). "For example, elevated TGF-β in patients with hepatitis B might "tune" CD4+ T cells with increased sensitivity to IL-6R signaling through inhibition of SOCS3." (PMID 21639870, 2011).
herpesvirus infection (1 paper, 2019). "The virologic, immunologic, and pathologic effects of SOCS1 or SOCS3 stimulation during herpesvirus infection frequently depend on cell type, virus strain, and host or host organ system." (PMID 31031749, 2019). "In addition to these findings with SOCS1 and SOCS3, a few studies also explore the effects of SOCS2 during α-herpesvirus infection." (PMID 31031749, 2019).
HIV-1 infection (1 paper, 2019). The type species of lentivirus and the etiologic agent of acquired immunodeficiency syndrome (AIDS). "So, to find out the possible advantage of HIV-1 mediated temporal regulation of SOCS3 to the virus itself, we investigated the effect of SOCS3 on HIV-1 infection." (PMID 30766526, 2019). "Expression of SOCS3 followed by VSV-G pseudotyped HIV-1 infection in CHME3 cells led to enhanced replication of HIV-1 as observed by increased levels of p24." (PMID 30766526, 2019). "Hence, our study explains the differential regulation of SOCS3 during HIV-1 infection and uncovers a novel role of SOCS3 in the regulation of NF-κB signaling and host immune evasion of HIV-1." (PMID 30766526, 2019).
hookworm infection (1 paper, 2008). "As for TLR2, low expression of SOCS-3 was associated with S. haematobium rather than hookworm infection." (PMID 18414649, 2008).
hypersensitivity (1 paper, 2022). An inflammatory response to an exogenous environmental antigen or an endogenous antigen initiated by the adaptive immune system. "All these findings demonstrated that SOCS3 was expressed in CRF neurons in PVN, with the downregulation of SOCS3 expression in CRF neurons in PVN implicated in the neonatal‐CRD‐induced chronic visceral hypersensitivity." (PMID 35702948, 2022).
hyperthyroidism (1 paper, 2016). Overactivity of the thyroid gland resulting in overproduction of thyroid hormone and increased metabolic rate. "Also opposite to the results obtained in TRs KO mice, hyperthyroidism resulted in increased hepatic levels of IL-6 and SOCS3 transcripts in response to 5 mg/kg LPS or 20 mg/kg LPS, while TNFα and IL-10 mRNAs remained unchanged." (PMID 27484112, 2016).
hypopharyngeal carcinoma (1 paper, 2018). Carcinoma, predominantly squamous cell, arising from the epithelial cells of the hypopharynx. "The results of SOCS-1, SOCS-3, and NF-κB are available on the analysis of the pathogenesis of hypopharyngeal carcinoma." (PMID 30788302, 2018). "The mRNA and protein expression levels of SOCS-1, SOCS-3 and NF-κB p65 in hypopharyngeal carcinoma tissues, para-cancerous tissues and control tissues were detected by RT-PCR and Western blot analysis, respectively." (PMID 30788302, 2018). "SOCS-1, SOCS-3 may be protective factors while NF-κB p65 could be a harmful factor in hypopharyngeal carcinoma." (PMID 30788302, 2018). "SOCS-1 and SOCS-3 may function as a tumor suppressor in hypopharyngeal carcinoma." (PMID 30788302, 2018). "SOCS-1 and SOCS-3 mRNA levels and protein levels were lower in hypopharyngeal carcinoma tissues than in pericarcinoma tissues, and the advanced stage patients had significantly lower level mRNA expression of SOCS-1 and SOCS-3 than those at early stages." (PMID 30788302, 2018).
insomnia (1 paper, 2025). A sleep disorder characterized by difficulty in falling asleep and/or remaining asleep. "We conducted WB experiments to detect the differences in protein expression levels of BCL2, SOCS3, and IL7R indicators in hippocampal neurons of normal control and insomnia model groups." (PMID 39833072, 2025). "In conclusion, our study verified that apoptosis is closely related to the development of insomnia, and BCL2, SOCS3, and IL7R have the potential to be therapeutic targets for insomnia." (PMID 39833072, 2025). "In this study, BCL2, SOCS3, and IL7R were all under-expressed in the hippocampal neurons of the insomnia model compared with the control group, suggesting a decreased antiapoptotic capacity." (PMID 39833072, 2025). "Through bioinformatic data analysis, we clarified that apoptosis signaling pathway plays an important role in the development of insomnia, and that the 3 hub genes, BCL2, SOCS3, and IL7R, are most likely involved in the development of insomnia." (PMID 39833072, 2025). "A total of 190 differentially expressed apoptosis-related genes were identified in insomnia, and BCL2, SOCS3, and IL7R were identified as important hub genes." (PMID 39833072, 2025). "Overall, our results indicate that BCL2, SOCS3, and IL7R may play important regulatory roles in the development of insomnia." (PMID 39833072, 2025). "Importantly, the decrease in BCL2, SOCS3, and IL7R indexes indicated that the antiapoptotic capacity of hippocampal neurons in the insomnia model group was weakened, and thus it is highly likely that BCL2, SOCS3, and IL7R are important targets in the development of insomnia." (PMID 39833072, 2025). "Although BCL2 has been studied in the context of sleep deprivation, SOCS3 and IL7R have not yet been explored in insomnia." (PMID 39833072, 2025).
intestinal tumors (1 paper, 2023). "This might suggest that SOCS3 had different functions in intestinal tumors with different anatomical locations and might influence the anatomical location of metastasis." (PMID 37025997, 2023).
intrahepatic cholestasis (1 paper, 2022). A cholestasis characterized by impairment of the bile flow caused by obstruction located in the liver. "SOCS3 expression is decreased in the placentas of women with intrahepatic cholestasis, which suggests an essential role of SOCS3 in the pathogenesis of this disease." (PMID 36587196, 2022).